NR4A1 (nuclear receptor subfamily 4 group A member 1)
Diseases named in the same sentence as NR4A1 in open-access papers (continued):
Sharing a sentence is not in itself a finding about the gene and the disease.
tumor (continued). "Among the many factors known to regulate anti-tumor immune responses, NR4A1 is an emerging critical regulator of many cell types within the TME." (PMID 40508074, 2025). "Remarkably, Nr4a1−/− mice treated with αPD‐1 exhibited a pronounced reduction in tumor burden and extended OS, accompanied by significantly lower Ki67 expression in lung tumors compared to control mice." (PMID 40552757, 2025). "They found that a new antineoplastic compound called 2-imino-6-methoxy-2H-chromone-3-carbothioamide (IMCA), which targets the MTC NR4A1 (orphan nuclear receptor 4A1), triggered tumor cell death in a dose-dependent manner." (PMID 40956676, 2025). "They found that NR4A1 can suppress tumor growth by interacting with another protein called c-Fos, which is involved in gene regulation." (PMID 40164686, 2025). "Given that NR4A1 promotes the progression of certain cancers, therapies targeting the protein have been investigated and found to augment anti-tumor immunity." (PMID 40508074, 2025). "NR4A1 plays multiple roles in different T cells populations within the TME that affect tumor immune responses." (PMID 40508074, 2025). "These cells were also clearly distinct from the tumor-associated CD69+IFNG+PRF1– and the dysfunctional/low cytotoxic NR4A1+ CD158a (KIR2DL1)+ CD158e (KIR3DL1)+ NK cell populations described in the other studies." (PMID 40530504, 2025). "Our results agree with the role of MALAT1 as a tumor suppressor maintaining NR4A1 expression in MCF7 cells." (PMID 38791553, 2024). "NR4A1 is reported to be downregulated in TNBC and restoration of NR4A1 expression inhibits TNBC growth and metastasis, suggesting that NR4A1 is a tumor suppressor in TNBC." (PMID 39777114, 2024). "Anti-CCL6, but not anti-CCL9, antibody reduced the recruitment of NK cells and prevented tumor regression by MDP in Nr4a1–/– mice, indicating that I-NCMs promote tumor regression by the CCL6-induced recruitment of NK cells." (PMID 39545417, 2024). "In human cancer, NR4A1 has a conflicting role, acting both as a tumor suppressor and an oncogenic driver." (PMID 38297314, 2024). "Bisulfite sequencing of Hrasls, Ret, Nr4a1, and Fgfr4 revealed inter- and intra-tumor heterogeneity in the DNA methylation of promoter regions." (PMID 38297314, 2024). "We did not detect significant changes in CD8+ Texh cells, TI-Tregs, or -NK cells upon NR-V04 treatment while controlling for tumor size, but certainly acknowledge that NR4A1 and its family members are important for these TI lymphocyte populations." (PMID 38334978, 2024). "In other cancers, NR4A1 promotes tumor progression via various mechanisms such as the promotion of epithelial-mesenchymal transition (EMT), invasiveness, and metabolic adaptation." (PMID 39872303, 2023). "After tumors reached a size of approximately 100 mm3 animals were treated with both CDIM/NR4A1 antagonists at either 2.5 or 7.5 mg/kg/day for 21-days and compared to control (corn oil) animals, treatment with CDIMs significantly decreased tumor volumes." (PMID 37847301, 2023). "Lithium can also promote proliferation and programmed cell death (PCD) in tumor cells through a number of new targets, such as the nuclear receptor NR4A1 and Hedgehog-Gli." (PMID 36831437, 2023). "We also observed that both NR4A1 antagonists inhibited tumor growth and downregulated PD-L1 in tumors demonstrating the highly effective intratumoral anticancer activity of these compounds." (PMID 37847301, 2023). "Our findings revealed that the distribution of NR4A1 was more extensive, and the expression levels were higher in tumor samples as compared to normal colon samples." (PMID 37564873, 2023). "Western blot analysis of tumor lysates from three animals showed that both CDIM/NR4A1 antagonists (2.5 mg/kg/d) decreased expression of NR4A1 and PD-L1." (PMID 37847301, 2023). "In AML, it functions as a tumor suppressor, and NR4A1-deletion facilitates AML development in mouse models." (PMID 39872303, 2023).
tumor (continued). "The observed protective effect of NR4A1 in both models suggests its role in regulating tumor survival and relapse." (PMID 37564873, 2023). "Genome-wide studies have identified NR4A1 as a key mediator of T-cell dysfunction and NR4A1 also plays an important role in regulating genes which are involved in tumor-induced T-cell exhaustion." (PMID 37847301, 2023). "And lastly, CD8+ T cells in the tumor periphery exhibited a transcription factor profile of exhausted T cells with high expression of NR4A1, MAF, and IRF4, which were implicated in T cell dysfunction and exhaustion." (PMID 38127790, 2023). "The advantages of this model in studying the effects of NR4A1 antagonists are also that modulation of T-cell exhaustion by these compounds can be observed in both tumor and spleen cell infiltrating lymphocytes." (PMID 37847301, 2023). "To assess for a role of Nr4a1 in tumor infiltrating monocytes we performed flow cytometry using intracellular Nur77 and qPCR from Ly6C sorted monocytes from combo resistant and IgG CTL treated tumors." (PMID 37449205, 2023). "Recently, the lipid metabolic roles of NR4A1 attracted more and more attention in tumor progression, especially fatty acid metabolism." (PMID 36052242, 2022). "Previous studies have shown that NR4A1 acts as a tumor suppressor in both lymphoid and myeloid cells, resulting in growth inhibition and induction of apoptosis." (PMID 35110542, 2022). "Collectively, these data revealed that Nr4a factors, particularly Nr4a1 and Nr4a2, play important roles in the maintenance of tumor Treg cells." (PMID 35514961, 2022). "More and more NR4A1 ligands are found to participate in tumor metabolic reprogramming, suggesting that regulating NR4A1 by novel ligands is a promising approach to alter metabolism signaling pathways in cancer therapy." (PMID 36052242, 2022). "Targeting NR4A1 was shown to be effective in reducing tumor growth in multiple types of cancer, highlighting the importance of NR4A1 in driving tumor progression." (PMID 35740522, 2022). "Through analyzing the transcriptome data in GEPIA2, GEO (GSE7803, GSE7410 and GSE39001), GENT2 and TIMER2.0 databases, we found that NR4A1 mRNA expression was lower in CC tissues than in non-tumor tissues." (PMID 36566195, 2022). "In the present study, the oncogenic role of NR4A1 in driving PTC tumor cell proliferation and clinical progression of PTC patients is described." (PMID 35110542, 2022). "Cytosporone B (CsnB) is an NR4A1 agonist; it induced tumor cell apoptosis and inhibited tumor growth in C57 mice via translocating NR4A1 to mitochondrial to cause cytochrome C release." (PMID 36052242, 2022). "In blood-derived cancers, NR4A1 is a tumor suppressor, whereas in solid tumors NR4A1 exhibits pro-oncogenic activities." (PMID 35563670, 2022). "Taken together, all these data indicate that NR4A1 functions as tumor suppressor and dramatically abrogates the malignant phenotype induced by METTL3 in CC cells." (PMID 36566195, 2022). "Since HIF-1 is a vital regulator in glutamine metabolism, NR4A1 is likely to become a potential target of tumor glutamine metabolism." (PMID 36052242, 2022). "And the tumor suppresser gene of Nr4a1 in TNBC was decreased cancer cell proliferation and invasiveness." (PMID 35768767, 2022). "Depending on the subcellular localization, intracellular abundance and transcriptional activity, NR4A1 functions either as a tumor suppressor or enhancer in many cancer types." (PMID 36566195, 2022). "A significantly higher level of NR4A1 expression was found in tumor stage four relative to tumor stage one and three." (PMID 35547878, 2022). "NR4A1 increases the level of PD-1 and TIM-3, and NR4A1-deficient T cells produce more IFN-γ and TNF and mediate tumor regression more significantly." (PMID 33668122, 2021). "Here, we demonstrate that SPDEF acts as a tumor suppressor by transcriptionally activating NR4A1 in HNSCC." (PMID 34667150, 2021).
tumor (continued). "In contrast, NR4A1 knockout promoted tumor growth coincident with increased ID1 expression in tumor tissues." (PMID 33990575, 2021). "Several studies have shown that NR4A1 promotes or inhibits tumor progression depending on the tumor type, cell-specific context, and various external stimuli." (PMID 34209871, 2021). "Tumor masses were increased by ~70% and decreased by ~40% in transgenic EC-NR4A1-S mice and EC-NR4A1-DN mice, in which the full length and a dominant negative mutant of NR4A1 were induced and specifically expressed in the mouse endothelium." (PMID 33634114, 2021). "Extending previous findings that tumor growth was inhibited in NR4A1 knockout mouse models, metastasis of colorectal tumor was completely inhibited in NR4A−/− mice." (PMID 33634114, 2021). "Silencing endothelial NR4A1 inhibits the proliferation and migration of tumor cells, indicating that the NR4A1 receptor functions as a regulator of tumor growth and metastasis in vivo." (PMID 33634114, 2021). "SPDEF exerted its tumor suppressive effects by directly regulating the NR4A1/oncogenic signaling axis in HNSCC." (PMID 34667150, 2021). "Bis-indole derived (CDIMs) bind the orphan nuclear receptor 4A1 (NR4A1) and inhibit NR4A1-regulated cancer cell and tumor growth." (PMID 34072371, 2021). "The role of NR4A1 in the TME has been further recognized with in vivo studies of tumor metastatic spreading models in wild-type (NR4A1+/+) mice and NR4A1−/− mice." (PMID 33634114, 2021). "The role of NR4A1 in regulating apoptosis appears to be tissue- or tumor type-specific, and more research is needed to elucidate this complex regulation." (PMID 33172112, 2020). "Overexpression of NR4A1 inhibits effector T cell differentiation, whereas deletion of NR4A1 overcomes T cell tolerance and increases T cell proliferation, enhancing anti-tumor effects." (PMID 32117960, 2020). "It recently has been reported that NR4A1 is overexpressed in tumors from NSCLC patients and is associated with tumor recurrence, suggesting its involvement in chemotherapy resistance." (PMID 33172112, 2020). "That is the case of Nr4a1, Ccl2, and Ccl3, which antagonize tumor growth by attracting tumor-suppressive immune cells." (PMID 33330473, 2020). "The results indicated that fenretinide at an effective blood concentration induced NR4A1 expression, reduce tumor burden, and promote the apoptosis of AML cells in AML mouse models." (PMID 31839811, 2019). "The apoptosis analysis results indicated that down‐regulating NR4A1 inhibited the Lnc‐NA‐mediated promotion of tumour cell apoptosis." (PMID 31050196, 2019). "Orphan nuclear receptor 4A1 (NR4A1) plays a pivotal role in regulating the proliferation and apoptosis of a variety of tumor cells." (PMID 29498706, 2018). "The TGF-β pathway and NR4A1 have been shown to play a key role in maintaining cellular homeostasis, and tumor suppressive and tumor promoting activities have been reported for both of these factors." (PMID 30213113, 2018). "The orphan nuclear receptor 4A1 (NR4A1) plays a pivotal role in regulating the proliferation and apoptosis in a variety of tumor cells." (PMID 29498706, 2018). "To search for an explanation, we examined NR4A1 protein by Western blotting in 231-Ctrl and 231-NR4A1 tumors that were respectively harvested at weeks 9 and 12 when tumor sizes in both groups became comparable." (PMID 28903348, 2017). "NR4A1 maintains levels of endoplasmic reticulum stress and reactive oxygen species (ROS) in tumor cells to facilitate cell proliferation and survival." (PMID 29207620, 2017). "When their tumor sizes reached ̃2 cm in diameter (late stage), NR4A1 protein in individual tumors was further reduced to low or negative levels." (PMID 28903348, 2017). "NR4A1 has been paradoxically reported as both a tumor suppressor and a cancer driver in previous studies, depending on different types of cancers, different cell lines of the same cancer type or different cohorts of patients." (PMID 28903348, 2017).
tumor (continued). "To assess the tumor suppressor function of NR4A1 in the inhibition of TNBC growth in vivo, we injected 231-Ctrl, 231-NR4A1#1 and 231-NR4A1#2 cells into the mammary gland fat pads of female SCID mice and measured their tumor growth rates." (PMID 28903348, 2017). "Examination of publically-available RMS array data show that NR4A1 mRNA is more highly expressed in RMS tumors compared to non-tumor tissue." (PMID 27144436, 2016). "We have previously shown that the AML tumor suppressors, NR4A1 and NR4A3 function redundantly in Kasumi-1 AML-ETO positive human AML cells to inhibit AML cell growth and reprogram a subset of AML gene expression signatures." (PMID 26938745, 2016). "Kidney injury can induce NR4A1 expression in non-tumor tissue, and one study reported the NR4A1 was expressed in 786-O cells and NR4A1 mRNA was more highly expressed in tumors from patients with RCC compared to surrounding non-tumor tissue." (PMID 26035713, 2015). "Validation of these results by semiquantitative and real-time PCR confirmed the increased expression of NR4A1 in tumour cells." (PMID 20642837, 2010). "Furthermore, in hepatocellular carcinoma, NR4A1 overexpression in NK cells drives their exhaustion, promoting tumor growth and metastasis by suppressing IFN-γ production and hindering additional immune cell activation against the tumor, such as T cells." (PMID 40508074, 2025). "Together, these findings suggest that NR4A1 plays a tumor-suppressive role in BC." (PMID 40164686, 2025). "In addition, NR4A1 facilitated metabolic adaptation in melanoma cells upon glucose deprivation to support tumor cell survival." (PMID 40164686, 2025). "Additionally, this review also highlights potential therapeutic strategies targeting NR4A1, leading to its inhibition, activation, or degradation to restore immune cell function and enhance anti-tumor immunity." (PMID 40508074, 2025). "Nevertheless, NR4A1 regulates a wide range of processes including metabolism, angiogenesis, inflammation, and immune cell differentiation, which could be involved in tumor initiation and progression." (PMID 39980141, 2025). "The cell ratio bar graph revealed that the C0 TCL1A+ Naive B cells subpopulation accounted for the largest proportion of samples of peripheral blood origin, and the C1 NR4A1+ Memory B cells subpopulation accounted for the largest proportion of samples of tumor origin." (PMID 39744570, 2025). "The results above confirmed the tumor-suppressive role of NR4A1 in BC growth, suggesting that restoring the activity or expression of NR4A1 might be a therapeutic strategy for inhibiting BC growth." (PMID 40164686, 2025). "NR4A1 potentially leads to targets for the control of tumor development." (PMID 40666103, 2025). "Many conventional small molecular ligands including 1,1-bis(3′-indolyl)-1-(p-hydroxyphenyl) methane (DIM-C-pPhOH), kaempferol, quercetin, CCE9, celastrol, etc., have been identified as inhibitors of NR4A1 that can impact both tumor intrinsic and extrinsic cancer immune responses." (PMID 40508074, 2025). "Orphan nuclear receptor 4A1 (NR4A1, Nur77) plays a crucial role in regulating immune cell metabolism and function within the tumor microenvironment (TME), thus influencing cancer progression and serving as a potential therapeutic target for cancer immunotherapy." (PMID 40508074, 2025). "Contrary to these findings, NR4A1 has also been reported to promote the tumor metastasis of BC23." (PMID 40164686, 2025). "Notably, NR4A1 exhibits a dual role in cancer, it can act as either a tumor suppressor or promoter, depending on the cellular context, particularly via the TGF-β signaling pathway." (PMID 40539060, 2025). "Moreover, global metabolome screening indicated that the deletion of NR4A1 resulted in tumor lipid remodeling and phospholipid accumulation, which was accompanied by increases in fatty acid and lipid uptake." (PMID 40164686, 2025).
tumor (continued). "This transformation could be associated with the expression levels of genes such as PDGFRB, PGF, JUN, and NR4A1, which play crucial roles in tumor development, angiogenesis, and cell proliferation." (PMID 39484208, 2024). "In contrast, transferring Nr4a1-proficient PMo into these mice impedes tumor invasion in the lung." (PMID 38408977, 2024). "NR4A1 influences tumor cell proliferation, while NR4A2 promotes M2 polarization." (PMID 37533434, 2023). "Nur77 (NR4A1) is a transcription factor first observed in pheochromocytoma (PC12) tumor cells." (PMID 36653355, 2023). "However, it should be noted that these effects are observed in mouse models and in the future humanized animal models and the relative effects of NR4A1/ligands on tumor vs immune cells in their overall anticancer activities will be investigated." (PMID 37847301, 2023). "However, in HCC, NR4A1 is low expressed, upregulating NR4A1 by CsnB or other compounds, such as 4-(quinoline-4-amino), can inhibit tumor cell growth in vitro and in vivo." (PMID 36052242, 2022). "NR4A1 is involved in the EMT in tumor metastasis and migration." (PMID 35600274, 2022). "Several previous studies have shown that NR4A1 can promote tumor cells’ EMT." (PMID 35600274, 2022). "Interestingly, NR4A1 exhibits both tumor-suppressive and pro-oncogenic effects in cancer development." (PMID 35600274, 2022). "Given the importance of LEF1 on driving tumor initiation and progression, we surmised that NR4A1 might stimulate PTC tumor aggressiveness through the LEF1 pathway." (PMID 35110542, 2022). "NR4A1 inhibition reversed the tumor suppressive effects of SPDEF in HNSCC cells." (PMID 34667150, 2021). "The data indicate that the 3,5-disubstituted compounds were NR4A1 antagonists and we hypothesized that their in vivo activity as inhibitors of tumor growth would be similar to or greater than the buttressed analogs of CDIM8." (PMID 34072371, 2021). "NR4A1 regulates cancer cell growth, survival, migration, and invasion, and bis-indole-derived compounds (CDIMs) that bind NR4A1 act as antagonists and inhibit tumor growth." (PMID 34072371, 2021). "Since it is known that NR4A1 induces cell apoptosis in several tumor types, we investigated whether the expression of NR4A1 re-sensitizes TamR cells to tamoxifen treatment by increasing apoptotic ability." (PMID 34209871, 2021). "Treg-specific Nr4a1 and Nr4a2 deficient mice have increased tumor resistance and pharmacological treatments that inhibit the expression of these NR4As in tumoral Treg cells result in improved CD8+ T cell functions and tumor control." (PMID 33597928, 2020). "NR4A1 is reported to have both oncogenic and tumor suppressor functions in human cancer." (PMID 33172112, 2020). "NR4A1 deletion enhanced immunity against tumor and chronic virus." (PMID 31892342, 2019). "Therefore, our study shows that Lnc‐NA can inhibit the progression of tumours by possibly affecting NR4A1 expression." (PMID 31050196, 2019). "Furthermore, Lnc‐NA regulated NR4A1 expression and activated the apoptosis signalling pathway to inhibit tumour progression." (PMID 31050196, 2019). "Compared with non-tumor tissues, NR4A1 is strongly expressed in the nucleus of tumor tissues, whereas inhibition of the expression of NR4A1 may decrease cell proliferation and increase cell apoptosis." (PMID 29498706, 2018). "In agreement with the role of FGFR1 in promoting cell proliferation and carcinogenesis, a number of iFGFR1-upregulated genes are cancer-driving genes such as ETS1, PIM1, NRG1, MMP1, and FOXQ1, while some iFGFR1-downregulated genes are tumor suppressors such as NR4A1 and GDF15." (PMID 30111373, 2018). "Interestingly, our results have shown that mRNA levels of both Nr4a1 and Nr4a3 were increased in spleen during the early stage of tumor progression and were decreased during advanced stages." (PMID 30037009, 2018). "Our findings suggest that NR4A1 is a tumor suppressor in TNBC." (PMID 28903348, 2017).